TMPRSS3 (transmembrane serine protease 3)
Diseases named in the same sentence as TMPRSS3 in open-access papers (continued):
Sharing a sentence is not in itself a finding about the gene and the disease.
hearing loss (continued). "A previous study indicated that mutations in the transmembrane protease serine 3 (TMPRSS3) gene, which encodes a transmembrane serine protease, cause nonsyndromic hearing loss (NSHL)." (PMID 32235586, 2020). "Mutations in the autosomal genes TMPRSS3, TMC1, USHIC, CDH23 and TMIE are known to cause hereditary hearing loss." (PMID 24416283, 2014). "Furthermore, over 30 genes associated with hearing loss are small enough to fit within the scAAV vector, including some of the most prevalent causes of hearing loss worldwide, such as GJB2 and TMPRSS3 (Table EV1)." (PMID 40859056, 2025). "Although TMPRSS3 has been shown to activate epithelial sodium channels (ENaC) and impact the level of the calcium-activated potassium (BK) channel KCNMA1, the exact role of TMPRSS3 in hearing—and by association in hearing loss—is poorly understood." (PMID 38691166, 2024). "Except for the relatively high frequency of two Scandinavian variants in the TMPRSS3 gene found in Polish patients with hearing impairment, recurrent causes of GJB2-negative hearing loss in Slavic populations remain largely unknown." (PMID 39273284, 2024). "Potential causative variants were identified in genes associated with nonsyndromic hearing loss (CIB2, COL11A1, ILDR1, MYO15A, TMPRSS3, and WFS1), nonsyndromic hearing loss or Usher syndrome (CDH23, MYO7A, PCDH15, and USH2A), and other syndromic forms of hearing loss (CHD7, OPA1, and SPTLC1)." (PMID 34837038, 2022). "Individuals with mutations in TMPRSS3 (transmembrane protease, serine 3) present with two different phenotypes: DFNB10-associated hearing impairment that is prelingual (OMIM 605511) and DFNB8-associated hearing impairment that is typically late onset and postlingual (OMIM 601072)." (PMID 28695016, 2017). "A combination of one TMPRSS3 (c.208delC) and one GJB2 (c.35delG) variant was detected in the proband’s maternal uncle, who does not have hearing impairment." (PMID 31412945, 2019).
breast carcinoma (6 papers, 2013 to 2022). "Recently, we reported that TMPRSS3 SNP rs3814903 associated with both breast cancer risk and survival and SNP rs11203200 associated with breast cancer survival." (PMID 26014348, 2015). "In our study, the only SNP associated with both breast cancer risk and survival was TMPRSS3 rs3814903." (PMID 25029565, 2014). "The strongest single marker association was with TMPRSS3 intronic variant rs11203200; the minor allele carriers had a greater than 1.6-fold risk of developing breast cancer compared with the major allele homozygotes." (PMID 25029565, 2014). "This resulted in the identification of two upregulated genes (DPEP1 and MMP11) as mutated in colon cancer and another three protease genes mutated in breast cancer (TMPRSS3, ADAM12 and MMP10)." (PMID 24243807, 2013). "Low expression levels of hepsin and TMPRSS3 are associated with poor breast cancer survival." (PMID 27841306, 2016). "Consequently, combined TMPRSS1 and TMPRSS3 mRNA expression and combined hepsin and TMPRSS3 protein expression were tested for statistical association with clinicopathological parameters and breast cancer-specific survival." (PMID 26014348, 2015). "Only TMPRSS3 rs3814903 associated with both the risk of breast cancer and survival." (PMID 25029565, 2014). "Another breast cancer risk-associating TMPRSS3 variant in our study was rs3814903." (PMID 25029565, 2014). "With regard to clinical significance, TMPRSS3 acts as a pro-oncogene in breast cancer, pancreatic cancer, glioma, gastric cancer, and nasopharyngeal cancer." (PMID 36081667, 2022). "We think that our results give emphasis to the role of altered expression of hepsin and TMPRSS3 in promoting breast tumor progression and metastasis as their role in breast cancer is still rather unexplored." (PMID 26014348, 2015). "Immunohistochemical staining was used to evaluate hepsin levels in 372 breast cancer samples and TMPRSS3 levels in 373 samples." (PMID 26014348, 2015). "Nonetheless, our study presents in a coherent clinical breast cancer sample set that TMPRSS3 is a credible prognostic biomarker." (PMID 26014348, 2015). "In the multivariate Cox regression survival analysis, low mRNA expression of TMPRSS1 (P = 0.023; HR, 2.065; 95 % CI, 1.106-3.856) and TMPRSS3 (P = 0.013; HR, 2.106; 95 % CI, 1.167-3.800) remained independent factors for predicting poor breast cancer survival." (PMID 26014348, 2015). "When local breast cancer relapses and distant metastasis were studied together, low TMPRSS3 mRNA and protein expression remained independent factors that affected relapse in the Cox regression analyses." (PMID 26014348, 2015). "Low TMPRSS1 and TMPRSS3 expression remained independent factors affecting breast cancer-specific survival in the Cox regression analysis." (PMID 26014348, 2015). "We found a notable difference in TMPRSS1 and TMPRSS3 mRNA expression between benign samples and grade I malignant tumors in that grade I breast cancer samples expressed considerably higher levels of TMPRSS1 and TMPRSS3 than benign samples." (PMID 26014348, 2015). "Low TMPRSS1 and TMPRSS3 mRNA expression levels were independent prognostic factors for poor breast cancer survival during the 20-year follow-up (TMPRSS1, P = 0.023; HR, 2.065; 95 % CI, 1.106–3.856; TMPRSS3, P = 0.013; HR, 2.106; 95 % CI, 1.167–3.800)." (PMID 26014348, 2015). "In closing, this study expands our knowledge of the biological processes behind breast cancer by investigating hepsin and TMPRSS3 expression in human breast tumors." (PMID 26014348, 2015). "TMPRSS1 and TMPRSS3 mRNA expression was high in well-differentiated malignant breast tumors compared to benign breast tumors." (PMID 26014348, 2015). "SNPs in TMPRSS3 (rs3814903 and rs11203200), TMPRSS7 (rs1844925), and HGF (rs5745752) associated significantly with breast cancer risk (Ptrend = 0.008–0.042)." (PMID 25029565, 2014).
breast carcinoma (continued). "TMPRSS3 SNPs rs3814903 and rs11203200, TMPRSS7 SNP rs1844925, and HGF SNP rs5745752 associated significantly with breast cancer risk (Poverall = 0.029, 0.008, 0.042, and 0.017, respectively)." (PMID 25029565, 2014). "These previous findings prompted us to investigate whether altered expression of hepsin and TMPRSS3 might also have a role in the molecular pathology of breast cancer." (PMID 26014348, 2015). "When overexpressed in breast cancer, hepsin and TMPRSS3 could promote cancer cell invasiveness via dysregulated proteolytic activity." (PMID 26014348, 2015). "Structurally, TMPRSS3 is almost identical to hepsin, and here we have shown that their mRNA and protein expression patterns are very similar in different phases of breast carcinogenesis and correlate with breast cancer prognosis." (PMID 26014348, 2015). "This is the first study to examine TMPRSS3 gene expression in a set of clinical breast cancer samples and to investigate whether altered TMPRSS1 and TMPRSS3 gene expression has an impact on the clinical outcome of breast cancer patients." (PMID 26014348, 2015). "The results suggest that the TTSPs hepsin and TMPRSS3 may have similar biological functions in the molecular pathology of breast cancer." (PMID 26014348, 2015). "To address this hypothesis, we genotyped tagging SNPs (tagSNPs) of five TTSP genes, TMPRSS1, TMPRSS2, TMPRSS3, TMPRSS7, and TMPRSS11E, two other serine proteases uPA and PRSS8, and HGF, and investigated their association with breast cancer risk and patient survival." (PMID 25029565, 2014). "This is the first study to link altered TMPRSS3 expression to breast cancer tumor progression and to show that low TMPRSS1 and TMPRSS3 expression, both at the mRNA and protein levels, has prognostic value for poorer survival of breast cancer patients." (PMID 26014348, 2015). "Although no studies have previously evaluated the role of TMPRSS3 in breast cancer, it is overexpressed in epithelial ovarian cancer, and is a potential diagnostic marker and therapy target." (PMID 25029565, 2014).
pancreatic cancer (4 papers, 2011 to 2023). "TMPRSS3 is overexpressed in pancreatic cancers when compared with normal pancreatic and pancreatitis tissues." (PMID 21654678, 2011). "TMPRSS3 is a membrane-bound serine protease overexpressed in pancreatic cancer." (PMID 36610719, 2023). "Moreover, biocomputational tools allowed to demonstrate that among the most differentially expressed genes in pancreatic cancer were Mesothelin, Muc4, Muc5A/C, Kallikrein 10, Transglutaminase 2, Fascin, TMPRSS3 and Stratifin." (PMID 25275504, 2014).
breast tumors (3 papers, 2015 to 2017). "TMPRSS3 is very important in the auditory system and was also identified as a tumor-associated gene that is overexpressed in pancreatic, ovarian, and breast tumors." (PMID 28246597, 2017). "The function of TMPRSS3 is very important to the auditory system; it has also been identified as a tumor-associated gene that is overexpressed in pancreatic, ovarian, and breast tumors." (PMID 28695016, 2017). "TMPRSS1 mRNA overexpression is associated with ER(α)-positive human breast tumors, while TMPRSS3 overexpression has been implicated in pancreatic and epithelial ovarian cancers." (PMID 26014348, 2015).
epithelial ovarian cancer (3 papers, 2014 to 2022). "TMPRSS3 is overexpressed in epithelial ovarian cancer and is a potential diagnostic marker and therapy target." (PMID 25029565, 2014). "And the expression levels of TMPRSS3, DMC1, and HLA-DO in ovarian cancer tissue are significantly lower than those in normal ovarian tissue." (PMID 36081667, 2022).
nasopharyngeal carcinoma (2 papers, 2022 to 2023). A carcinoma arising from the nasopharyngeal epithelium. "Outside the inner ear, TMPRSS3 is highly expressed in several malignancies, including breast, ovarian, pancreatic, gastric, nasopharyngeal carcinoma, and brain gliomas." (PMID 37663645, 2023).
nonsyndromic deafness (2 papers, 2004 to 2020). An auditory system disease that is associated with permanent hearing loss caused by damage to structures in the inner ear and/or the middle ear, which is not associated with other signs and symptoms. "TMPRSS3 is the only protease reported thus far to be involved in nonsyndromic deafness." (PMID 15447792, 2004).
ampullary cancers (1 paper, 2016). "This 3-gene expression model suggests that the collective expression of IRX3, PYCR1, and TMPRSS3 reflects the additional biological importance of tumor invasion, intestinal differentiation, and cellular metabolism, in the prognosis of ampullary cancers." (PMID 27549176, 2016).
benign breast tumors (1 paper, 2015). "TMPRSS1 mRNA expression was determined in 125 invasive and 16 benign breast tumor samples, and TMPRSS3 mRNA expression was determined in 167 invasive and 23 benign breast tumor samples." (PMID 26014348, 2015). "In benign breast tumor cells, the expression levels of TMPRSS1 and TMPRSS3 are consistently low, whereas the expression levels are higher in cancer cells." (PMID 26014348, 2015).
colon cancer (1 paper, 2013). "Additionally, we were able to identify other genes highly upregulated in tumor samples, including ABHD7, TMPRSS3 or OTUB2, which had not been previously associated with this pathology, and might constitute novel candidate genes for colon cancer." (PMID 24243807, 2013).
colorectal cancer (1 paper, 2020). A primary or metastatic malignant neoplasm that affects the colon or rectum. "TFF1e is an intronic eRNA located at the TMPRSS3 gene at transmembrane protease serine 3, which is a pro-metastatic mediator found to have higher expression in breast, pancreatic, and colorectal cancers." (PMID 32466143, 2020).
Pleural effusion (1 paper, 2025). The presence of an excessive amount of fluid in the pleural cavity. "We also identified pleural effusion predictive gene signatures, including TMPRSS3, MS4A7, NAPSA, and IGFBP2, while liver metastasis predictive markers included WFDC2, HSPB1, COX6C, APOE, and TUBA1A." (PMID 39955556, 2025).
retinoblastoma (1 paper, 2020). A malignant tumor that originates in the nuclear layer of the retina. "For example, we found germline P/LP variants in TMPRSS3, a member of the serine protease family, in patients with CNS tumors, retinoblastoma, and soft tissue sarcoma." (PMID 32371905, 2020).
sensorineural hearing loss (1 paper, 2017). "The developed approach was validated by searching for pathogenic variants in the TMPRSS3 gene in a cohort of 2247 subjects with sensorineural hearing loss (SNHL)." (PMID 28566687, 2017).
tumor (8 papers, 2013 to 2025). "Mechanistically, Tmprss3 overexpression can decrease E-cadherin levels and thereby disrupt cell-cell adhesion, leading to tumor invasiveness and metastasis." (PMID 37663645, 2023). "The increased expression of IRX3 and TMPRSS3 in the poor prognosis ampullary subset is consistent with the biological functions of these genes in promoting tumorigenesis and tumor invasion, respectively." (PMID 27549176, 2016). "Further, low expression levels of TMPRSS1 and TMPRSS3 mRNA and hepsin and TMPRSS3 predict advanced tumor malignancy and poorer prognosis." (PMID 26014348, 2015). "In the multivariate survival analysis of TMPRSS3 expression, ER-negative status and lobular histology were independent prognostic factors in addition to positive nodal status and large tumor size." (PMID 26014348, 2015). "Notably, since matriptase and hepsin have identical substrates and since both have possible tumor progression and metastasis-promoting activities, further studies of TMPRSS3 are needed to better understand its functions and substrates." (PMID 26014348, 2015).
cancer (6 papers, 2015 to 2023). A tumor composed of atypical neoplastic, often pleomorphic cells that invade other tissues. "Several type II transmembrane serine proteases similar to TMPRSS3 are implicated in the development and progression of different types of cancer." (PMID 37663645, 2023). "B3GNT7, TIAM2 and TMPRSS3 were all found to promote the proliferation, invasion and migration of cancer cells." (PMID 32385351, 2020). "Based on bioinformatic analysis of possible binding proteins at TMPRSS3 and due to its high expression, TMPRSS3 is considered a key regulator of cancer pathways." (PMID 32466143, 2020). "TMPRSS3 can mediate cancer progression, using its proteolytic activities, by helping the malignant cells to proliferate, migrate, and survive, via regulation of the ERK1/2 and PI3K/AKT pathways." (PMID 32371905, 2020). "Hepsin, (also called TMPRSS1) and TMPRSS3 are type II transmembrane serine proteases (TTSPs) that are involved in cancer progression." (PMID 26014348, 2015). "Importantly, this is also the first cancer study to show that altered TMPRSS3 expression has prognostic value for cancer-related death." (PMID 26014348, 2015). "Furthermore, H19 regulated many other cancer-related genes in this network, such as AKT3, CSF1, MET, COL1A1, COL5A1, WWTR1, EPHB4, and TMPRSS3." (PMID 31164794, 2019).
TMPRSS3 also shares sentences with these, for which no sentence is quoted: Hearing impairment (9 papers); autosomal recessive deafness (8); Usher syndrome (3); ovarian cancer (2); (CACP) Syndrome (1); Alzheimer’s dementia (1); autosomal recessive disease (1); Autosomal Recessive Hearing Loss (1); brain glioma (1); CNS tumors (1); Down syndrome (1); gastric cancer (1); glioma (1); Hypertension (1); infection (1); invasive breast carcinoma (1); Marfan syndrome (1); nephrotic syndrome (1); Obesity (1); pancreatitis (1); prostate carcinoma (1); pseudohypoaldosteronism type 1 (1); retinitis pigmentosa (1); soft tissue sarcoma (1); Usher syndrome type 3A (1).